BRCA1 (BRCA1 DNA repair associated)
Diseases named in the same sentence as BRCA1 in open-access papers (continued):
Sharing a sentence is not in itself a finding about the gene and the disease.
glioma (48 papers, 2014 to 2025). A benign or malignant brain and spinal cord tumor that arises from glial cells (astrocytes, oligodendrocytes, ependymal cells). "Recent studies have found that higher levels of BRCA1 expression are associated with lower survival in low-grade gliomas." (PMID 38977680, 2024). "In recurrent glioma patients, higher BRCA1 expression is associated with worse prognosis, especially the ones that received TMZ-treated." (PMID 38977680, 2024). "Its mutational analysis identified previously identified hereditary gene changes such as MSH6 known to confer susceptibility to glioma, BRCA1 germline mutation which is extremely rare in gliomas, as well as a novel mutation EWSR1 in glioma." (PMID 35370679, 2022). "DNA-PKcs deficient glioma cells are highly dependent on FEN1/BRCA1/RAD51 to survival and counteract replication stress." (PMID 35414100, 2022). "Combining these effects of LCS-1 in glioma cells, it induces death of glioma cells through the similar mechanism compared to that PARP inhibitors induce cell death in BRCA1/2 deficient cells." (PMID 35978820, 2022). "Clinically, the altered ratio of BRCA1 variants would undermine the survival of glioma patients who need standard temozolomide treatment." (PMID 27835581, 2016). "Higher BRCA1 positivity is associated with shorter survival of glioma patients and the abrogation of BRCA1 function in GBM enhances RS, DNA damage (DD) accumulation and impairs tumour growth." (PMID 27845331, 2016). "According to the CGGA database, BRCA1 expression is strongly correlated with poor prognosis in patients with recurrent glioma, particularly those who underwent TMZ treatment." (PMID 38977680, 2024). "Analysis of the two datasets suggested that the expression of BRCA1 in recurrent glioma was markedly greater than that in primary glioma." (PMID 38977680, 2024). "In low-grade gliomas, the mechanism of BRCA1 in epithelial mesenchymal transition, mitotic spindle, and glycolysis also deserves further study." (PMID 37759912, 2023). "It has been reported that BRCA1/hsa-miR-212 axis plays a potential role in the radiotherapy of gliomas by regulating apoptosis." (PMID 36523600, 2022). "Inhibition of FEN1 induces homologous recombination deficiency through impaired expression and assembly of BRCA1 and RAD51 in multiple glioma cell types and sensitizes these cells to the effects of DNA-PKcs deficiency." (PMID 35414100, 2022). "Evidently, the development of PARP inhibitors to date has been focused on monotherapy use in tumors harboring BRCA1/2 mutations or other HRD, which are uncommon in gliomas." (PMID 35205750, 2022). "Expression levels of risk factors BRCA1, DNM1L, RCN1, HSPB1, RPN2, LRRK2 and SPP1 in high‐grade gliomas were greater than those in lower‐grade gliomas, while the protein expression levels of protective factor PDIA3 were exactly the opposite." (PMID 33611848, 2021). "Our work illustrated this at the molecular level as BRCA1’s expression was significantly increased in glioma cells, while the expression of LARP4B was decreased." (PMID 34482648, 2021). "We found that the expression of KIF4A and BRCA1 was significantly correlated with each other in glioma (R = 0.76 and p-value < 0.001), providing a functional link between RBP and gene." (PMID 32047515, 2019). "Activated Fn14 also induces SGEF expression, which modulates the function of the DNA damage response protein BRCA1 to augment glioma cell survival in the presence of TMZ." (PMID 28103571, 2017). "BRCA1 high patients showed significantly shortened survival compared with BRCA1 low patients when either ALL gliomas or just GBM patients were analysed." (PMID 27845331, 2016). "The mean BRCA1 positivity was increased in WHO grade II gliomas (mean=5.92%) compared with NB (P=0.5344, n.s., One-way ANOVA and Tukey’s multiple comparisons test)." (PMID 27845331, 2016).
glioma (continued). "Another study proposed that BRCA1 expression is regulated by miR-212, affecting radiosensitivity and may affect the efficacy of radiotherapy for glioma." (PMID 38801243, 2024). "The expression of BRCA1 in recurrent glioma was positively correlated with AKT." (PMID 38977680, 2024). "In literature, only BRCA1, TRIM21, and POLR2F have been implicated in the progression of glioma." (PMID 36118697, 2022). "Gliomas exhibit pronounced genomic instability and develop a dependence on BRCA1." (PMID 33804958, 2021). "In glioma, the expression of BRCA1, RUNX1, and SERPINE1 were analyzed using GSEA." (PMID 33723286, 2021). "Abrogation of BRCA1 had also been found to play roles in tumor growth in glioma." (PMID 32047515, 2019). "Furthermore, we validated these findings by ‘in silico’ analysis of the publically available REMBRANDT glioma dataset (GlioVis web application), which confirmed the positive correlation between BRCA1 and RRM2 mRNA expression (SCA; P=0.00; CI 0.44–0.57)." (PMID 27845331, 2016). "Given the pronounced genomic instability and endogenous RS in gliomas, we reasoned that these tumours may develop dependence on BRCA1, a hypothesis tested in the present study." (PMID 27845331, 2016). "However, several tumor types do not show BRCA1/2 mutations, and the genomic instability in those tumors is marked by translocations and fusions (gliomas and hematological malignancies) compared to copy number changes." (PMID 37761823, 2023). "For gliomas, it is notable that IDH mutations may induce a phenotype similar to BRCA1/2 mutations." (PMID 35205750, 2022). "Moreover, as FEN1 regulates the expression and function of many molecules, there may be additional effects of FEN1 inhibition that contribute to sensitization of glioma cells to DNA-PKcs dysfunction, either cooperating with BRCA1/2, RAD51 or WRN." (PMID 35414100, 2022). "A distinct glioma stem cell population was identified, characterized by high proliferative potential and an enrichment of E2F1, E2F2, E2F7, and BRCA1 regulons, with implications for tumor growth and patient outcomes." (PMID 39981232, 2025). "To explore the relationship between BRCA1 and TMZ resistance, we analyzed clinical and bioinformatics data from patients with recurrent glioma in the CGGA database." (PMID 38977680, 2024). "Our analysis results showed that BRCA1 and HDAC1 were highly expressed in gliomas, while the expression results of RANGAP1 were opposite." (PMID 38801243, 2024). "Our study revealed that the AKT inhibitor perifosine decreases BRCA1 expression, potentially reversing TMZ resistance in patients with recurrent glioma." (PMID 38977680, 2024). "The discovery of key prognostic genes, particularly BRCA1, HDAC1, and RANGAP1, highlights their significant impact on glioma survival." (PMID 38801243, 2024). "In glioma disease, RRM2 can promote human glioblastoma cell proliferation, migration and invasion and RRM2 expression controlled by BRCA1 can protect glioblastoma cells from endogenous replication stress while also increasing tumorigenicity." (PMID 36750807, 2023). "Transcripts of VV-GMCSF-Lact-infected glioma and NB cells that directly correlate with CD50 are enriched with mRNAs controlled by transcription factors ATF2, BRCA1, CREB1, ELF1, TAF1, UBTF, and YY1." (PMID 37998351, 2023). "Lin established a 6-RBP gene signature consisting of POLR2F, DYNC1H1, SMAD9, TRIM21, BRCA1, and ERI1 in another bioinformatics work, allowing for a complete assessment of glioma and ischemic stroke." (PMID 37884559, 2023). "In all WHO grade II-IV gliomas, DNAss was positively correlated with the RBPS score, ERI1, BRCA1, and TRIM21, while negatively correlated with POLR2F, DYNC1H1, and SMAD9 [Spearman correlation, Benjamini-Hochberg (BH)-adjusted p < 0.05]." (PMID 36118697, 2022).
glioma (continued). "The volcanic plot showed the differential analysis results of these six RBP genes, which showed that POLR2F and DYNC1H1 were downregulated in glioma, while TRIM21, BRCA1, ERI1, and SMAD9 were upregulated in glioma." (PMID 36118697, 2022). "First, six prognostic-related RBP genes (POLR2F, DYNC1H1, SMAD9, TRIM21, BRCA1, and ERI1) were obtained from the TCGA-glioma dataset." (PMID 36118697, 2022). "GSEA revealed significant enrichment of pathways including DNA replication, cell cycle, and homologous recombination with BRCA1 and RAD51 in the glioma samples." (PMID 35414100, 2022). "Among them, POLR2F, DYNC1H1, and SMAD9 in tumor tissues of patients with glioma were downregulated as compared to normal tissues adjacent to cancer, while TRIM21, BRCA1, and ERI1 were upregulated." (PMID 36118697, 2022). "Elevated BRCA1 and RAD51 level were also observed in glioma patient samples compared with normal samples." (PMID 35414100, 2022). "We found that BRCA1, CHD1 and FoxM1 mRNA expression was significantly positively correlated with ASPM mRNA expression in glioma tissues, and the highest correlation coefficient was found between FoxM1 and ASPM expression." (PMID 32667745, 2020). "The validation study using the REMBRANDT glioma dataset (ALL gliomas and GBM) confirmed the prognostic significance of BRCA1 and RRM2 mRNA expression in malignant gliomas." (PMID 27845331, 2016). "Spearman correlation analysis (SCA) for association revealed a positive correlation between the percentage of BRCA1+ and RRM2+ cells in our glioma cohort (correlation coefficient=0.24; P=0.0039)." (PMID 27845331, 2016). "Our study presents that BRCA1, BRCA2 and RAD51 are increased in the two glioma cell lines following treatment with TMZ." (PMID 25337721, 2014). "Given the findings that HR-DNA repair proteins (BRCA1, BRCA2 and RAD51) are significantly increased in TMZ-resistant glioma cells, an abundance expression of BRCC3 in glioma cells seems likely to foster HR-dependent DNA repair processes." (PMID 25337721, 2014). "By preferentially activating the DNA damage checkpoint response to control the cell cycle, boost DNA repair capacity, and decrease radiosensitivity by upregulating the expression of HR genes RAD51-, BRCA1/2-, and CD133-positive glioma stem cells help to develop glioma radioresistance." (PMID 37322433, 2023). "We labeled FEN1, BRCA1 and RAD51 in glioma mouse samples and observed decreased BRCA1 and RAD51 expression upon treatment with the specific FEN1 inhibitor sc13, confirming the regulatory role of FEN1 on BRCA1 and RAD51 in glioma cells." (PMID 35414100, 2022). "BRCA1 promoted the GBM cell growth and negatively decreased the survival of gliomas." (PMID 36233273, 2022). "Taking together, these results suggest that the degradation of both PARP and BRCA1 may contribute to cell death induced by SOD1 inhibition, and SOD1 may be a target for glioma therapy." (PMID 35978820, 2022). "Both BRCA1 and RRM2 were determined to be negative prognostic factors for glioma patient survival and implicated in tumor development." (PMID 33804958, 2021). "Our present findings provide the first clear evidence that BRCA1 positivity increases with increasing degree of malignancy in human gliomas and serves as a negative prognostic factor for patient survival." (PMID 27845331, 2016). "Additionally, RRM2 expression positively correlated with that of BRCA1 and both the percentage of BRCA1+ and RRM2+ cells correlated negatively with glioma patient survival, thus making RRM2 an attractive candidate for therapeutic targeting in GBM." (PMID 27845331, 2016). "Next, we sought to determine whether there is a correlation between BRCA1 and RRM2 expression in our clinical glioma cohort." (PMID 27845331, 2016). "In addition, BRCA1, BRCA2 and RAD51 are required for HR-dependent DNA repair pathway in TMZ-resistant glioma." (PMID 25337721, 2014). "Therefore, FEN1 is a key regulator of BRCA1 and RAD51 protein levels and function in glioma cells." (PMID 35414100, 2022).
glioma (continued). "Cases with at least one somatic copy-number deletion in any of the HR genes (excluding BRCA1/2) showed significantly higher HRD scores compare to cases without deletions in OV, BRCA, Sarcoma (SARC), TGCT, adrenocortical carcinoma (ACC), low grade glioma (LGG), and UCEC (FDR < 0.05)." (PMID 34572800, 2021). "In glioma, genome-wide association studies have identified common genetic variations in 7 genes that increase glioma risk (TERT, EGFR, CCDC26, CDKN2A, CDKN2B, PHLDB1 and RTEL1) but BRCA1 is not among them and there is no known association between BRCA1 gene and glioblastoma multiforme (GBM)." (PMID 25880076, 2015). "Indeed, here we show that BRCA1 is a negative prognostic factor for glioma patient survival." (PMID 27845331, 2016). "In this study, we found that the mutant genes in the metastatic brain tumors included ALK, MDM2, ATM, BRCA1, FGFR1, and KRAS, and there were no glioma-related mutant genes (MGMT, IDH1, IDH2, 1p/19q, BRAF, and TERT)." (PMID 32973641, 2020). "Importantly, our present results provide the first evidence of BRCA1 and its down-stream effector RRM2 as negative prognostic factors for glioma patient survival." (PMID 27845331, 2016).
non-small cell lung carcinoma (48 papers, 2007 to 2026). A group of at least three distinct histological types of lung cancer, including non-small cell squamous cell carcinoma, adenocarcinoma, and large cell carcinoma. "Nevertheless, due to their often-observed high mutational burden (e.g., due to smoking), about 5–10% of non-small cell lung cancer cases show somatic mutations in either the BRCA1 or BRCA2 gene." (PMID 34145376, 2021). "In a recent series of 102 non-small-cell lung cancer patients, high levels of BRCA1 mRNA were associated with better response and decreased risk of progression to gemcitabine plus docetaxel." (PMID 20209131, 2010). "It induces homologous recombination DNA repair, by interacting with BRCA1 and hnRNPUL1, in Non-small cell lung cancer." (PMID 37509693, 2023). "Non-small-cell lung cancer (NSCLC) is known to demonstrate somatic alterations in BRCA1 or BRCA2 gene." (PMID 36577523, 2022). "Several studies demonstrated that high expression of BRCA1 shows a marker of platinum resistance in non-small-cell lung cancer(NSCLC)." (PMID 28404895, 2017). "We retrospectively analyzed 71 paraffin-embedded tumor samples from advanced non-small-cell lung cancer patients treated with first-line platinum based chemotherapy and measured the mRNA expression levels of BRCA1, RNF8, UBC13 and HERC2 using real-time PCR." (PMID 27179511, 2016). "In GBM, MPM and Non-Small Cell Lung Cancer (NSCLC) TTFields alter DNA repair through downregulation of BRCA1 (BReast CAncer gene 1) pathway genes and alteration of homologous recombination (HR) causing chromatid aberrations, DNA fragmentation and mitotic catastrophe." (PMID 40467542, 2025). "Among the non-BRCA-associated lineages with 500 or more patients, the rate of germline BRCA1/2 prevalence ranged from 2.6% (25/949) in hepatobiliary to 0.5% (3/604) in thyroid, and was 1.7% (77/4474) among patients with non-small cell lung cancer, which was the most common cancer type in our cohort." (PMID 36418296, 2022). "For instance, it has been reported that the aberrant expression of BRCA1 impairs the DNA damage repair machinery in certain tumors, and therefore, its expression levels can be an effective biomarker of survival for non-small-cell lung cancer patients with cisplatin-based chemotherapy." (PMID 36081518, 2022). "The features of BRCA1/2 germline mutations in non-small cell lung cancer (NSCLC) have not been systematically studied." (PMID 33563323, 2021). "Besides BRCA1/2 mutant cancers, veliparib has also been tested in other cancers such as non-small cell lung cancer (NSCLC) and melanoma, although results have been disappointing." (PMID 28829366, 2017). "Powerful metrics are available to detect FANCD2/BRCA1 foci formation, such as the FA triple-staining immunofluorescence based method (FATSI), which identified a subset of non-small-cell lung cancer (NSCLC) tumors that were deficient in FANCD2/BRCA1 foci and thus were repair deficient." (PMID 27642590, 2016). "Furthermore, BRCA1 mRNA expression levels predicted outcome following cisplatin-containing chemotherapy in non-small-cell lung cancer." (PMID 20209131, 2010). "Olaparib and rucaparib treatment modulate the immune response through the cGAS/STING pathway in ERCC1-defective, non-small cell lung cancer (NSCLC) and BRCA1-defective TNBC cells." (PMID 34885119, 2021).
non-small cell lung carcinoma (continued). "DNA damage repair proteins: BLM, BRCA-1 and PARP-1 expression decreased gradually.LYY-35 can inhibit the proliferation of non-small cell lung cancer A549 cells, block cell cycle, promote apoptosis, increase ROS production, cause DNA damage and interfere with DNA replication." (PMID 38947387, 2024). "Besides CRLs, NAE inhibition blocks the recruitment of the BRCA1 DNA damage repair complex and a combination with PARP inhibition inhibited cell growth of non-small cell lung cancer (NSCLC) cells." (PMID 33327527, 2020). "An example sentence is show below linked to the BRCA1 gene with gene id 672 from the citation with PubMed R identifier (PMID) 22093627: FISH-positive EGFR expression is associated with gender status, but not correlated with the expression of ERCC1 and BRCA1 proteins in non-small cell lung cancer." (PMID 23725347, 2013).